CD4 (CD4 molecule)
Diseases named in the same sentence as CD4 in open-access papers (continued):
Sharing a sentence is not in itself a finding about the gene and the disease.
AIDS (continued). "We have reviewed how we will work from a trinity of strategies to eradicate HIV and cure AIDS, to reprogram the immune repertoire function of memory CD4 T-cells and reconstitute patient anti-HIV immunity to cure AIDS with or without HAART." (PMID 24151495, 2013). "The latest policy guidance from WHO recommends that ART should be provided to all TB/HIV co-infected patients, irrespective of their CD4 cell count (and to all people living with HIV/AIDS with a CD4 cell count less than 350)." (PMID 23696901, 2013). "Moreover, the high occurrence of E. gingivalis in HIV(+)/AIDS patients can be influenced by multifactorial components not directly related to the CD4+ lymphocyte counts, such as cholesterol and the oral microbiota host, which could mask the potential opportunistic ability of E. gingivalis." (PMID 24376598, 2013). "Although CD4+ counts at HAART initiation are not known in these patients, individuals in the NIR group exhibited AIDS related symptomatology when they were first tested for HIV antibodies, whereas only 33% of the HIR patients did." (PMID 23967152, 2013). "Trials evaluating treatment interruptions in adults have reported higher rates of AIDS events/death and serious non-AIDS events in those stopping ART, and the SMART trial reported that CD4-guided episodic use of ART resulted in inferior quality of life (QOL)." (PMID 22584916, 2013). "From the 995 individuals in the three SSA cohorts, we excluded 251 individuals: 105 had seroconverted pre-2000, 94 were not infected through sex between men and women, and 52 had one or no CD4 counts while ART-naïve and AIDS-free." (PMID 22412867, 2012). "None of the classic markers of HIV-related immunodeficiency, including low CD4+ cell counts, high HIV viral load nor history of AIDS or AIDS-related pulmonary disease, showed any clear association with lung cancer in the SHCS." (PMID 22240797, 2012). "The authors compared the incidence of PCP to the incidence in 1665 patients at the Multicenter AIDS Cohort Study (MACS) who were not on HAART and not receiving any prophylaxis against PCP with CD4 counts <200 cells/μL." (PMID 22194853, 2011). "In the absence of CD4 testing in rural primary health care facilities, WHO HIV/AIDS clinical staging is used to recommend when to initiate ART." (PMID 21589912, 2011). "After adjusting for sex, age, baseline CD4 count, year of HAART initiation, and type of regimen, the hazard of change was 1.3 times higher for a person with clinical AIDS prior to HAART initiation than a person without (95% CI: 1.1 to 1.5)." (PMID 20531956, 2010). "We have estimated the rate of LTFU between initial enrolment in pre-ART care for patients not yet eligible for ART (baseline CD4 > 250 cells/μl) and their first scheduled return visit at one of South Africa's largest HIV/AIDS treatment facilities." (PMID 20586959, 2010). "Multivariate factors associated with a greater increase in BMI during HIV infection included more recent year of diagnosis, lower BMI at diagnosis, higher CD4 count, lower HIV RNA level, lack of AIDS diagnosis, and longer HIV duration (all p<0.05)." (PMID 20419086, 2010). "Among HIV-related variables, ART was more common in the most recent period; however, no significant changes occurred over time from diagnosis, CD4 cell count, HIV load, and number of patients admitted for their first AIDS-defining episode." (PMID 20534139, 2010). "Survival was longer for IDUs with higher CD4+ T-cell counts, but this information was missing for 68.0% of patients (most of whom had received a diagnosis of HIV without AIDS)." (PMID 19214229, 2009). "Plasma LPS, but not sCD14 levels, were higher in AIDS patients co-infected with HCV compared to HCV- subjects, even though plasma VL was lower and CD4 counts were higher in HCV+ compared to HCV- subjects." (PMID 18575590, 2008).
AIDS (continued). "Surprisingly, sCD14 levels were not increased in AIDS patients with substance abuse or HCV coinfection; however, these subjects had higher CD4 counts and lower plasma VL compared to control groups, indicating a less advanced stage of HIV disease." (PMID 18575590, 2008). "In the four years preceding AIDS diagnosis, a non-significant change in HIV RNA increase was seen, whereas a significant biphasic pattern was present for CD4 T-cell decline." (PMID 17888148, 2007). "Higher CD4 counts also predicted lower non-fatal CCO incidence after NHL and KS, although, particularly for NHL, this, to a large extent, was attributed to other AIDS events." (PMID 41463249, 2025). "Other risk factors (e.g., interruption of antiretroviral therapy, medication adherence, HIV viral load, CD4/CD8 ratio, etc.)that may affect mortality in HIV/AIDS were not included in this analysis because more detailed data were not available." (PMID 38778273, 2024). "However, few existing studies have been specially designed to explore the relationship between the CD4/CD8 ratio and specific types of non–AIDS-related events, notably liver damage." (PMID 37846087, 2024). "We analyzed the correlation between CD4 count or pVL at pre-cART and the frequency of positive T-cell responses to epitopes under cART in 90 individuals, including 78 non-AIDS HIV-1 patients and 12 AIDS patients." (PMID 37877716, 2023). "In general, the lack of significant effects of low CD4 cell count, high HIV-RNA viral load, and female sex on BMI trends after ART initiation could be due to lack of power or due to the adjustment for AIDS at baseline in our model." (PMID 36016299, 2022). "The man was a late presenter (CD4+ count < 350/mmc/AIDS defining illness regardless of the CD4+ cell count at HIV diagnosis) with an HIV RNA viral load in plasma of 650,000 cps/mL, accompanied by CD4+ count of 9/mmc (2.4%), CD8+ count of 347.2/mmc (54.2%), and CD4+/CD8+ ratio of 0.04." (PMID 35447880, 2022). "Eventually, this balance is lost and CD4+ T cell numbers decline to the point that effective immune responses against HIV and other pathogens can no longer be mounted, resulting in progression to AIDS." (PMID 35693831, 2022). "A total of 66 individuals had at least one component of primary study outcome: 27 individuals reached a CD4 T lymphocyte count below 350 cells/μL, 57 individuals started ART, and no individual reached an AIDS-defining event as a primary outcome, and no one died during the study period." (PMID 35834528, 2022). "Similarly, a Spanish cohort found that in five-year survivors without history of AIDS-defining events, there was no survival differences between those starting ART with CD4 count >350 cells/μL or with 200–350 cells/μL." (PMID 35958520, 2022). "A decline of initial ART prescriptions during hospitalization was observed, which is likely due to guideline changes by the International Antiviral Society–USA Panel and the Korean Society for AIDS, leading to ART being offered to patients with HIV/AIDS regardless of CD4 cell counts." (PMID 35132147, 2022). "None of the HIV disease characteristics: nadir CD4 cell count (p = 0.97), time since HIV diagnosis (p = 0.35), diagnosis of AIDS (p = 1.00), ART status (p = 1.00), duration of ART (p = 0.52) and Efavirenz-based ART regimes (p = 0.45) were found to be associated with Global Neurocognitive Impairment." (PMID 34348754, 2021). "The Turkish HIV/AIDS Guideline, which is compatible with international guidelines on strategies to screen and therapies to treat HIV/AIDS, has encouraged initiating ART regardless of CD4+ T lymphocyte count since 2013." (PMID 35222560, 2021). "We studied the association between hypertension and other possible confounding factors on viral load and CD4-cell counts in hypertensive and non-hypertensive HIV/AIDS patients receiving antiretroviral therapy (ART) at a large hospital in Eswatini over a 4-year period." (PMID 34155234, 2021).
AIDS (continued). "We have not considered dynamic changes in CD4+ cell counts during follow-up, which may influence survival in HIV/AIDS patients." (PMID 34592916, 2021). "On the other hand, when CD4 count data are not used (using default CD4 assumptions), estimates of the time from infection to diagnosis are not very robust, as they rely only on data of HIV/AIDS and AIDS diagnoses (ECDC modelling tool) or AIDS deaths (CSAVR)." (PMID 32590964, 2020). "Among the 87 cases of HIV/AIDS patients without PCP, the CD4+ T cell numbers of 42 cases (48.28%) are below 100 ×106/L, while 45 patients (51.72%) have CD4+ T cell numbers >100 ×106/L, among which 22 cases (25.29%) have >200 ×106/L, with the highest value being 1,382 ×106/L." (PMID 32911508, 2020). "However, other studies have suggested that CD28/HLA-DR expression on CD4+ T cells, but not on CD8+ T cells, is an important predictor for progression to AIDS." (PMID 32187205, 2020). "Although the Kaposi sarcoma (KS) is one of the AIDS defining entity and seen in almost one third of HIV infected patients with low CD4 cell counts, it is not uncommon in HIV seronegative persons, but genital KS is rare, particularly in people without risk factors for HIV infection." (PMID 31827596, 2019). "The Kenya AIDS Indicator Survey of 2012 reported ART coverage among all HIV-infected adults of about 35%, and that 31% of HIV-infected adults not on ART had CD4+ counts below 350 cells/μl, 15% had CD4+ counts 350–500 cells/μl, and 55% CD4+ counts above 500 cells/μl." (PMID 31805028, 2019). "In this context, considerable amount of attention has been paid to understand the hallmark feature of HIV infection, i.e., progressive depletion of CD4 lymphocytes, and its distinct regulation in HIV-infected individuals in whom infection never progresses to AIDS or progresses very slowly." (PMID 28588579, 2017). "However, the Th17 cells exacerbate cryptococcal disease when both CD4 and CD8 T cells are lacking, such as in individuals with HIV/AIDS." (PMID 29333430, 2017). "WHO published HIV/AIDS prevention and antiretroviral treatment guidelines in 2015 and strongly recommended that all individuals with HIV/AIDS should receive ART as soon as possible, regardless of CD4+ cell count." (PMID 28358846, 2017). "Though HIV/AIDS clinical guidelines did not recommend ART initiation for all HIV-seropositive patients during this study period, treatment for individuals with a CD4 count at or below 350 cells/mm3 shifted from a moderate to strong recommendation over this time period." (PMID 28700693, 2017). "A study in Brazil highlighted the occurrence of nosocomial severe infections and the great impact of sepsis on 1- and 6-month survival and confirmed that CD4 the T-cell count, the HIV RNA level, and other HIV/AIDS variables were not predictive of 30-day and 6-month outcomes." (PMID 27800179, 2016). "Age, duration of treatment, CD4+ cell count (in the HIV group) and pulse rate correlated positively with systolic dysfunction, while duration of treatment, diastolic blood pressure, and CD4+ cell count (in the AIDS group) demonstrated a negative correlation." (PMID 26956496, 2016). "The CD4/CD8 ratio did not add predictive information on morbidity to the CD4+ cells count, except for non-AIDS cancers for which a ratio < 0.5 constituted the main immunological predictor of these events with a twice higher risk of non AIDS cancer in patients with a CD4/CD8 ratio < 0.5." (PMID 27548257, 2016). "Older age was strongly associated with cardiovascular mortality and with non-AIDS non-liver malignancies, IDU with non-AIDS infection and liver-related mortality, and low CD4 count and detectable viral replication at ten years after starting ART with AIDS mortality." (PMID 27525413, 2016). "After more than 20 years of focusing on AIDS-defining opportunistic diseases (mostly infectious) at low CD4 counts, the focus thus becomes on non-AIDS HIV-related diseases (mostly non-infectious) at high CD4 counts." (PMID 27462361, 2016).
AIDS (continued). "Similarly, in an AIDS Malignancy Consortium study on rapamycin with HAART, no significant changes in IL-6 and VEGF plasma concentrations, viral load and CD4 counts were observed during KS monitoring." (PMID 26296972, 2015). "This apparent paradox could be related to the different pressures acting on CD4 and CD8 T cells or to the specific features of our cohort, which exclusively included long-term treated individuals (more than 2 years) without AIDS defining events." (PMID 26183947, 2015). "Therefore, pediatric HIV/AIDS patients without HAART, infected with intestinal parasites, and having low CD4+ T cell counts had 2.3, 2.7, and 3.8 times more likelihood of being anemic compared to their counterparts, respectively." (PMID 25878898, 2015). "Given the prominence of maternal deaths due to AIDS or TB in this setting, management of HIV before pregnancy and in pregnant women is critical – South African policy now places HIV-positive pregnant women on antiretrovirals irrespective of CD4 cell count." (PMID 26000547, 2015). "Those who have AIDS-defining opportunistic infections (i.e., PCP and neurotoxoplasmosis) have lower NKp46 expression and low DNAM-1/NKG2D/NCR:ligand ratios compared to patients who reach similarly low CD4+ cell counts but do not develop AIDS." (PMID 25071766, 2014). "To determine whether any of the miRNA measurements could be utilized for monitoring HIV/AIDS patients with or without ART, we determined the correlation between miRNA levels and the existing surrogate markers - CD4+ T-cell counts or viral loads." (PMID 24828336, 2014). "TB diagnosis before 2010, the presence of other AIDS-related diseases and non AIDS-related co-morbid conditions, not receiving CPT, not receiving ART, and having CD4 cell counts <50 cells/mm3 were identified as potential factors of death during TB treatment among TB/HIV co-infected patients." (PMID 25506830, 2014). "In addition, patients (a CD4 cell count of 350–500 cells/μL and regardless of WHO clinical stage of HIV/AIDS) who meet certain conditions are also recommended to start antiretroviral treatment." (PMID 24289721, 2013). "Despite this depletion, the CD4-low SIV infected mangabeys maintain low levels of systemic immune activation, preserve lymphoid architecture, preserve function of non CD4 T cells and most importantly, show no clinical signs of simian AIDS." (PMID 23825945, 2013). "The Drug Resource Enhancement Against AIDS and Malnutrition Programme has been promoting HAART use during pregnancy and postpartum for Prevention-of-mother-to-child-HIV transmission (PMTCT) irrespective of maternal CD4 cell counts since 2002." (PMID 23990966, 2013). "Furthermore, young age, high baseline CD4 count, low HIV viral load, no history of AIDS, non Japanese, no ART, and no health insurance/public assistance were associated with LTFU." (PMID 23951307, 2013). "However, this will not have significant influence on the interpretation as the CD4+ T cell count is used as part of the parameter for staging and found to be correlated with WHO stage of HIV/AIDS." (PMID 23710936, 2013). "In the three studies not reporting CD4 cell count but only reporting on HIV stage according to WHOs clinical AIDS definition the percentage of HIV positive TB patients defined as having AIDS varied from 61.8% to 76%." (PMID 21738585, 2011). "In addition, low CD4 cell counts, time since HIV diagnosis, HAART treatment or AIDS stage of disease; conversely, have not been identified as risk factors for ICU mortality in the post-HAART era." (PMID 22126648, 2011). "However co-infected individuals with reduced CD4 levels, indicative of AIDS had higher prevalence of HBeAg retention and elevated HBV DNA levels compared to non-AIDS patients with higher CD4 count." (PMID 20843322, 2010).
AIDS (continued). "Other factors associated with greater increases in BMI included a higher time-updated CD4 cell count (p<0.001), a lower time-updated HIV RNA level (all p<0.001 when compared to level >100000 copies/mL), lack of an AIDS diagnosis (p<0.001), and increased time since HIV infection (p<0.001)." (PMID 20419086, 2010). "While HIV-specific CD4+ T cells are preferentially infected and depleted by HIV, CMV-specific CD4+ T cells are often easily identifiable even in late stage HIV and evidence of CMV disease does not occur until endstage AIDS when CD4+ T cells counts are <100 and more often <50 cell/μl." (PMID 19876388, 2009). "Rates of AIDS defining event (ADE), serious ADE and death by CD4 and HIV RNA categories before and after combination antiretroviral therapy (cART) initiation are lacking for high CD4 counts." (PMID 18923700, 2008). "The increase in the anti-HIV antibody titer and rebound of the CD4+ T cell population correlates with the chronic stage of the HIV infection, which, in the absence of antiretroviral therapy, will progress to AIDS in 5 to 10 years, although the timeframe might vary greatly among individuals." (PMID 38667150, 2024). "Among our cohort, median CD4 counts at KS diagnosis (186, IQR: 55–341) and HIV VLs (49, IQR: 1–5553) indicate that KS diagnoses are not made exclusively in patients with uncontrolled HIV- and AIDS-related immune suppression but also in patients with controlled HIV infection." (PMID 38399965, 2024). "A low incidence of primary PCP in patients receiving cART who had virologically suppressed HIV infection, with CD4 cell counts < 200 cells/mL, irrespective of prophylaxis, was suggested based on data presented in an observational HIV epidemiological research in Europe among patients with AIDS." (PMID 38069248, 2023). "The results showed a significant negative correlation between CD4 count at pre-cART and the frequency of positive T-cell responses under cART in 12 AIDS patients, suggesting that HIV-1-specific T cells were effectively elicited under cART in AIDS patients with a lower CD4 count at pre-ART." (PMID 37877716, 2023). "HIV progresses to acquired immunodeficiency syndrome (AIDS) when a patient’s CD4+ cell count is below 200 cells/mm3 of blood or when a patient presents with any of a number of AIDS-defining illnesses (e.g. Kaposi sarcoma, HIV-related encephalopathy, Pneumocystis jirovecii) regardless of CD4+ count." (PMID 37303361, 2023). "We thus conclude that CD4+ T-cell depletion is not a determinant of SIV-related gut dysfunction, when gastrointestinal tract epithelial damage and inflammation are absent, suggesting that disease progression and resistance to AIDS are independent of CD4+ T-cell restoration in SIVagm-infected AGMs." (PMID 36813761, 2023). "Two men with HIV/AIDS accompanied by syphilis that both strongly opposed ART due to personal prejudices were each administered a single TCM in 2012; both lived stably with relatively normal levels of CD4+ counts and lower viral loads, and no side effects or complications were found." (PMID 35685631, 2022). "In our cohort, HIV-positive patients were significantly younger than the HIV-negative comparator, mostly virologically suppressed before COVID-19 and with a median CD4 count of 272 cells/μL; hence, these findings may not be applicable to a population with poorly controlled HIV or AIDS." (PMID 35329872, 2022). "Patients SP-FFB/2020 and SP-MJMS/2020 had CD4+ T cell count of 691 cells/mm3 and 752 cells/mm3 with HIV viral loads of 290, 976 copies/mL (5.46 log) and below the limit of detection (<50 copies/mL); both with diagnoses of syphilis without any AIDS-defining disease." (PMID 36067165, 2022). "While there are no effective interventions recommended to increase CD4 counts in PWH receiving ART, information from cohort studies may contribute to design better monitoring practices for early diagnosis and timely treatment of non-AIDS related events." (PMID 35602655, 2022).